DMD (dystrophin)
Diseases named in the same sentence as DMD in open-access papers (continued):
Sharing a sentence is not in itself a finding about the gene and the disease.
Duchenne muscular dystrophy (continued). "Duchenne muscular dystrophy (DMD) is a rare, severe, degenerative X-linked myopathy caused by mutations in the gene (DMD) encoding the dystrophin protein." (PMID 27594988, 2016). "Duchenne muscular dystrophy (DMD) is caused by the absence of the dystrophin protein, which acts to transmit force between cytoskeleton and extracellular matrix via the dystrophin glycoprotein complex (DGC)." (PMID 27977770, 2016). "Duchenne muscular dystrophy (DMD), the most common and severe form of muscular dystrophy, is an X-linked recessive genetic disorder caused by mutations in the gene that encodes dystrophin." (PMID 27073590, 2016). "Mutations in the dystrophin-encoding DMD gene cause X-linked dystrophinopathies with variable phenotypes, the most severe being Duchenne muscular dystrophy (DMD) characterized by progressive muscle wasting and fibrosis." (PMID 27382459, 2016). "Duchenne Muscular Dystrophy (DMD) is a progressive muscle wasting disorder that is caused by loss-of-function mutations in the DMD locus on the X-chromosome." (PMID 27466195, 2016). "Duchenne muscular dystrophy (DMD) is caused by mutations in the gene encoding dystrophin and four autosomal recessive subtypes of limb-girdle muscular dystrophy (LGMD) are caused by mutations in the sarcoglycans." (PMID 27999547, 2016). "Duchenne muscular dystrophy (DMD) is a severe progressive muscle disorder caused by mutations in the dystrophin gene located on the X-chromosome." (PMID 26997958, 2016). "Duchenne muscular dystrophy (DMD) is a degenerative and progressive muscular disease caused by the absence of the dystrophin protein, affecting about 1 in 3,500 male births and for which there is no effective therapy." (PMID 26083527, 2015). "Duchenne muscular dystrophy (DMD) is caused by mutations in the dystrophin gene (DMD), and is characterized by progressive weakness in skeletal and cardiac muscles." (PMID 25791035, 2015). "Duchenne muscular dystrophy (DMD) is a progressive and fatal muscle degenerating disease caused by a dystrophin deficiency." (PMID 26290039, 2015). "In Duchenne muscular dystrophy (DMD), the dystrophin (DMD) gene is mutated, leading to a loss of dystrophin protein." (PMID 25460248, 2015). "The utrophin-dystrophin deficient (DKO) mouse model has been widely used to understand the progression of Duchenne muscular dystrophy (DMD)." (PMID 25859846, 2015). "The X-linked disease Duchenne muscular dystrophy (DMD) is caused by mutations in the gene encoding the protein dystrophin." (PMID 25954502, 2015). "Recently, patient-derived iPSCs, containing identical genetic anomalies of the patient, have offered a breakthrough approach to studying Duchenne muscular dystrophy (DMD), a fatal disease caused by the mutation in the dystrophin gene." (PMID 26579330, 2015). "Although Duchenne muscular dystrophy is a monogenic disorder of the neuromuscular system with defined genetic abnormalities and distinct clinical features, the secondary pathobiochemical changes due to the primary loss of the membrane cytoskeletal protein dystrophin are extremely complex." (PMID 28248273, 2015). "Mdx mouse is the best characterized animal model of Duchenne muscular dystrophy (DMD), an X-linked lethal myopathy due to mutation in the gene of dystrophin, which is crucial for myofiber integrity during muscle contraction." (PMID 26759818, 2015). "Consider conventional genetic disease mutations, such as those causing Duchenne muscular dystrophy (DMD), affecting the dystrophin gene." (PMID 26136770, 2015). "In Duchenne muscular dystrophy (DMD) patients and murine mdx model of DMD, dystrophin deficiency causes a decrease in muscle and mislocalization of muscle specific isoform nNOSμ leading to dysfunction." (PMID 25883934, 2015). "The mdx mouse is the most frequently used animal model for Duchenne muscular dystrophy (DMD), a fatal muscle disease caused by the loss of dystrophin." (PMID 25737807, 2015).
Duchenne muscular dystrophy (continued). "Duchenne muscular dystrophy (DMD) is an X-linked inherited neuromuscular disorder due to mutations in the dystrophin gene." (PMID 26457695, 2015). "Duchenne muscular dystrophy (DMD) is an X-linked muscle disease caused by mutations in the DMD gene that code for dystrophin." (PMID 26380303, 2015). "Duchenne muscular dystrophy (DMD) is an X-linked recessive disorder caused by genetic mutation in the dystrophin gene and characterized by progressive muscle wasting and weakness." (PMID 25935002, 2015). "In dystrophin-deficient muscles of Duchenne Muscular Dystrophy (DMD) patients and the mdx mouse model, nitric oxide (NO) signalling is impaired." (PMID 26296873, 2015). "The most frequent form of muscular dystrophy is Duchenne Muscular Dystrophy (DMD), caused by mutations in the dystrophin gene and with an incidence of 1 in 3300 live male births." (PMID 25710816, 2015). "Another example is one of the therapy strategies of Duchenne muscular dystrophy (DMD), which is to induce the skipping of exons mutated to be poison exons in the dystrophin gene." (PMID 26400733, 2015). "Duchenne muscular dystrophy (DMD) results in loss of dystrophin, which disrupts structural scaffolds for dystrophin-associated proteins (DAPs) as well as specific signaling processes, causing progressive muscle loss with sterile inflammation." (PMID 26461208, 2015). "Duchenne muscular dystrophy (DMD) is a genetic muscle disorder caused by mutations in the Dmd gene resulting in the loss of the protein dystrophin." (PMID 25988613, 2015). "The X-linked recessive disease Duchenne muscular dystrophy (DMD) is caused by mutations in the gene encoding the protein dystrophin." (PMID 25954502, 2015). "The most common and severe muscular dystrophy is Duchenne muscular dystrophy (DMD), which is caused by mutations in the X-linked dystrophin gene." (PMID 26258142, 2015). "Among the diseases afflicting the skeletal muscle tissue is Duchenne muscular dystrophy (DMD), which is caused by frame shift mutations in the dystrophin gene located in the locus Xp21." (PMID 25763072, 2015). "Duchenne muscular dystrophy (DMD) is a hereditary X-linked neuromuscular disorder due to mutations in the dystrophin gene with a worldwide incidence of approximately 1:5,000 male newborns leading to progressive muscle atrophy and weakness." (PMID 25519771, 2014). "Duchenne muscular dystrophy (DMD), the most common X-linked lethal disorder in humans, is caused by defects of the gene encoding dystrophin, a 427 kDa cytoskeletal protein found at the inner surface of the skeletal muscle surface membrane." (PMID 25312642, 2014). "Duchenne muscular dystrophy (DMD) is an X-linked recessive disorder caused by mutations in the dystrophin gene." (PMID 25203313, 2014). "Duchenne muscular dystrophy (DMD) is an incurable disease that manifests in children and is caused by mutations in the dystrophin gene." (PMID 25127359, 2014). "Duchenne muscular dystrophy (DMD) is a X-linked recessive and progressive muscle disease caused by failure to express sarcolemmal protein dystrophin." (PMID 25181488, 2014). "Duchenne muscular dystrophy (DMD) is a neuromuscular disease that arises from mutations in the dystrophin-encoding gene." (PMID 25260053, 2014). "Mutations in DGC components cause different types of muscular dystrophy; for example, mutations in dystrophin cause Duchenne muscular dystrophy (DMD), while mutations in α-, β-, γ-, or δ-sarcoglycan (SG) cause limb girdle muscular dystrophy (LGMD)." (PMID 25024843, 2014). "Duchenne muscular dystrophy (DMD) is characterized by progressive muscle fiber degeneration as a result of a dystrophin deficiency at the muscle fiber sarcolemmal membranes." (PMID 25244123, 2014). "Mutations in the dystrophin gene cause the most common form of X-linked Duchenne muscular dystrophy (DMD)." (PMID 25221510, 2014).
Duchenne muscular dystrophy (continued). "Duchenne muscular dystrophy (DMD) is a severe X-linked myopathy of childhood that arises from the loss of dystrophin protein expression in cardiac and skeletal muscles." (PMID 24505439, 2014). "Duchenne muscular dystrophy (DMD) is one of the severest of the dystrophies and is caused by loss of the dystrophin protein due to genetic mutations." (PMID 25157321, 2014). "Muscle hypertrophy in the mdx mouse model of Duchenne muscular dystrophy (DMD) can partially compensate for the loss of dystrophin by maintaining peak force production." (PMID 24910770, 2014). "Duchenne muscular dystrophy (DMD) is caused by mutations in the dystrophin gene and afflicts skeletal and cardiac muscles." (PMID 25789154, 2014). "Golden Retriever Muscular Dystrophy (GRMD) is a dystrophin-deficient canine model genetically homologous to Duchenne Muscular Dystrophy (DMD) in humans." (PMID 24713872, 2014). "Duchenne Muscular dystrophy (DMD) is a devastating genetic muscle disorder caused by partial or complete loss of cytoskeletal protein dystrophin." (PMID 25364719, 2014). "Among these disorders, Duchenne muscular dystrophy (DMD) is a severe genetic disease resulting from mutation of the X-linked dystrophin gene." (PMID 24781921, 2014). "For instance, defects in components of the dystrophin-glycoprotein complex (DGC) are known to cause Duchenne muscular dystrophy (DMD), sarcoglycanopathies and some forms of congenital muscular dystrophy." (PMID 23798567, 2013). "In Duchenne muscular dystrophy (DMD), loss of the membrane stabilizing protein dystrophin results in myofiber damage." (PMID 23843959, 2013). "Duchenne muscular dystrophy (DMD) is a lethal X-linked disease in humans characterized by the absence of dystrophin protein, which leads to progressive muscle weakness, respiratory insufficiency, and cardiomyopathy." (PMID 24403852, 2013). "We describe two donor splice site mutations, affecting dystrophin exons 16 and 45 that led to Duchenne muscular dystrophy (DMD), through catastrophic inactivation of the mRNA." (PMID 24498612, 2013). "The X-linked recessive Duchenne muscular dystrophy (DMD) affects 1 in 3500 newborn boys, and it is caused by the loss of dystrophin expression." (PMID 24392452, 2013). "Duchenne muscular dystrophy (DMD) is caused by mutations in DMD, which encodes the protein dystrophin." (PMID 23169061, 2013). "Duchenne Muscular Dystrophy (DMD) is a recessive X-linked genetic disease, caused by mutations in the gene encoding dystrophin." (PMID 24349043, 2013). "Duchenne muscular dystrophy (DMD) results from mutations in the gene encoding dystrophin, a protein that stabilizes muscle cell membranes." (PMID 24349052, 2013). "Duchenne muscular dystrophy (DMD) caused by loss of cytoskeletal protein dystrophin is a devastating disorder of skeletal muscle." (PMID 23977226, 2013). "Mutations in the dystrophin gene lead to two more common type of dystrophy: the severe Duchenne muscular dystrophy (DMD OMIM 300677) due to out-of-frame mutations, and the milder Becker muscular dystrophy (BMD OMIM 300376) associated with in-frame mutations." (PMID 24084719, 2013). "The dystrophin-deficient dog is excellent large animal model for testing novel therapeutic modalities for Duchenne muscular dystrophy (DMD)." (PMID 23544107, 2013). "In particular, Duchenne muscular dystrophy (DMD), the most common form of muscular dystrophy, is caused by lack of dystrophin protein." (PMID 23984357, 2013). "For example, this approach has been successfully used to eliminate exon 51 mutations of dystrophin gene of patients with Duchenne muscular dystrophy (DMD)." (PMID 22938201, 2012). "The dystrophin gene, which is mutated in Duchenne muscular dystrophy (DMD), encodes a large cytoskeletal protein present in muscle fibers." (PMID 22238670, 2012). "For example, in Duchenne muscular dystrophy (DMD), muscle fibers undergo necrosis due to dystrophin deficiency." (PMID 22730231, 2012).
Duchenne muscular dystrophy (continued). "Duchenne muscular dystrophy (DMD) is a severe progressive muscular disorder caused by reading frame disrupting mutations in the DMD gene, preventing the synthesis of functional dystrophin." (PMID 22359642, 2012). "Loss of muscle force is a salient feature of Duchenne muscular dystrophy (DMD), a fatal disease caused by dystrophin deficiency." (PMID 22973449, 2012). "Duchenne muscular dystrophy (DMD) is a progressive and fatal disease of muscle wasting caused by loss of the cytoskeletal protein dystrophin." (PMID 22427904, 2012). "Degeneration of skeletal muscle can result as a consequence of injury or disease, as in Duchenne Muscular Dystrophy (DMD), the most frequent neuromuscular disorder in boys, caused by a defect in the dystrophin gene." (PMID 23239981, 2012). "In patients with Duchenne muscular dystrophy (DMD) and the standard mdx mouse model of DMD, dystrophin deficiency causes loss of neuronal nitric oxide synthase (nNOSμ) from the sarcolemma, producing functional ischemia when the muscles are exercised." (PMID 23139842, 2012). "Duchenne Muscular Dystrophy (DMD) is the most common muscular dystrophy in which mutations are found in the dystrophin gene that encodes the primary membrane anchor protein essential for skeletal muscle stability." (PMID 24524008, 2012). "Duchenne muscular dystrophy (DMD) is a recessive X-linked devastating muscle disease due to dystrophin-deficiency, affecting 1 newborn male in 3500, and for which to date no curative treatment exists." (PMID 23185260, 2012). "Duchenne muscular dystrophy (DMD) is an X-linked recessive disorder caused by mutations in the DMD gene." (PMID 22876130, 2012). "Duchenne muscular dystrophy (DMD), the most common and severe form of muscular dystrophy, is caused by mutations in the dystrophin gene, the largest gene identified in the human genome." (PMID 22340947, 2012). "Duchenne muscular dystrophy (Phenotype MIM number 310200) is caused by mutation in the gene encoding dystrophin (DMD; 300377) with location on Xp21.2-p21.1." (PMID 23114028, 2012). "Although the mdx mouse dystrophy is caused by similar genetic mechanisms to the human condition Duchenne Muscular dystrophy (DMD), causing a dystrophin protein deficiency, the murine phenotype is less severe than that in humans." (PMID 22183053, 2011). "Duchenne muscular dystrophy (DMD) is an X-linked recessive disease affecting approximately 1 in 3, 500 males and is caused by defects in the dystrophin gene." (PMID 22132688, 2011). "Duchenne muscular dystrophy (DMD) is a devastating muscle wasting disease caused by mutations in dystrophin, a muscle cytoskeletal protein." (PMID 22028826, 2011). "Duchenne muscular dystrophy (DMD) is a lethal X-linked disorder caused by mutations in the dystrophin gene, which encodes a cytoskeletal protein, dystrophin." (PMID 21479190, 2011). "Duchenne muscular dystrophy (DMD), which is caused by mutation of the dystrophin gene, is the most common and severe form of muscular dystrophy." (PMID 21639928, 2011). "Duchenne muscular dystrophy (DMD) is a severe muscle-wasting disease caused by mutations in the dystrophin gene." (PMID 21995957, 2011). "Duchenne muscular dystrophy (DMD) is an X-linked fatal neuromuscular disease caused by mutations in the dystrophin gene." (PMID 22216264, 2011). "Duchenne muscular dystrophy (DMD) is a lethal X-linked progressive muscle-wasting disease caused by mutations, typically large deletions in the DMD gene, the largest gene in the human genome." (PMID 21798085, 2011). "Antisense oligomer induced exon skipping aims to reduce the severity of Duchenne muscular dystrophy by redirecting splicing during pre-RNA processing such that the causative mutation is by-passed and a shorter but partially functional Becker muscular dystrophy-like dystrophin isoform is produced." (PMID 22013876, 2011). "Duchenne muscular dystrophy (DMD) is a severe muscle-wasting disorder caused by mutationsin the dystrophin gene." (PMID 22101343, 2011).
Duchenne muscular dystrophy (continued). "Duchenne muscular dystrophy (DMD) is a lethal, progressive muscle wastingdisease caused by a loss of sarcolemmal bound dystrophin, which results inthe death of the muscle fibers leading to the gradual depletion of skeletalmuscle." (PMID 21573153, 2011). "Duchenne muscular dystrophy (DMD) is a lethal X-linked recessive muscle wastingdisease caused by mutations in the dystrophin gene." (PMID 21573153, 2011). "Duchenne muscular dystrophy (DMD) is an X-linked recessive neuromuscular disorder, which is caused by dystrophin deficiency in muscle fibers." (PMID 21507246, 2011). "Mutations in the DMD gene cause Duchenne muscular dystrophy (DMD), which is associated with a loss or severe reduction of the dystrophin protein." (PMID 20975992, 2010). "Mutations in the dystrophin gene cause Duchenne muscular dystrophy (DMD), the most common severe childhood muscular pathology." (PMID 20531943, 2010). "The most common myopathies caused by a defect in the DAPC complex are Duchenne Muscular Dystrophy (DMD) and its milder form, Becker Muscular Dystrophy, which are both caused by mutations in the X−linked dystrophin gene." (PMID 20856896, 2010). "Duchenne Muscular Dystrophy (DMD) is an X-linked lethal disorder that affects 1 in 3500 male births and is caused by genetic mutation in the dystrophin gene." (PMID 21994713, 2010). "Duchenne muscular dystrophy (DMD) is a fatal muscle wasting disorder caused by mutations in the dystrophin gene." (PMID 20515474, 2010). "In exercised dystrophin deficient mice, chronic administration of Tβ4 increased the number of regenerating fibers in skeletal muscle and could have a potential role in treatment of skeletal muscle disease in Duchenne muscular dystrophy." (PMID 20126456, 2010). "Duchenne muscular dystrophy (DMD) is an incurable neuromuscular degenerative disease, caused by a mutation in the dystrophin gene." (PMID 19277212, 2009). "Duchenne muscular dystrophy (DMD) is a serious X-linked disease caused by mutations in the gene that encodes the cytoskeletal protein dystrophin." (PMID 19421321, 2009). "Sarcoglycan complex is also secondarily reduced in Duchenne muscular dystrophy (DMD), when dystrophin is missing, indicating that DMD muscle suffers from combined dystrophin and sarcoglycan complex deficiencies." (PMID 19333401, 2009). "Duchenne muscular dystrophy (DMD) is the most prevalent form of human muscular dystrophy and is caused by mutations in dystrophin, a 427 kDa cytoskeletal protein necessary for proper membrane stability in muscle." (PMID 19478831, 2009). "Its absence on muscle causes Duchenne Muscular Dystrophy (DMD), a severe disorder, while a defect of muscle dystrophin causes Becker Muscular Dystrophy (DMB), a milder disease." (PMID 19144182, 2009). "Duchenne Muscular Dystrophy (DMD) is an X-linked genetic disorder that results in the production of a dysfunctional form of the protein, dystrophin." (PMID 19236710, 2009). "Duchenne muscular dystrophy (DMD) is an X-linked, lethal disorder of skeletal muscle caused by mutations in the dystrophin gene, which encodes a large sub-sarcolemmal cytoskeletal protein, dystrophin." (PMID 18182116, 2008). "Duchenne muscular dystrophy (DMD), the most well-known of the nine major types of muscular dystrophy, is a severe muscle-wasting disease that arises from mutations in the dystrophin gene (Xp21.2) (review)." (PMID 16719929, 2006). "Duchenne muscular dystrophy (DMD) is a fatal genetic disease of childhood characterized by progressive skeletal muscle weakness resulting from mutation of DMD and loss of functional dystrophin." (PMID 41994144, 2026). "In humans, the history of branched fibers in disease date back to reports from Erb in 1891 and Krosing in 1892, where branching was first reported in boys with Duchenne muscular dystrophy (DMD), associated with deficiency of the sarcolemmal protein dystrophin." (PMID 41596335, 2026).